FGF23 (fibroblast growth factor 23)
Diseases named in the same sentence as FGF23 in open-access papers (continued):
Sharing a sentence is not in itself a finding about the gene and the disease.
type 2 diabetes (30 papers, 2013 to 2026). "A higher plasma FGF23 level also represents a risk factor for an increased risk of premature mortality and major adverse cardiovascular events in individuals with type 2 diabetes [62▪▪]." (PMID 40237064, 2025). "Recent reports showed that a higher blood FGF23 level is a novel predictor of all-cause and cardiovascular mortality in patients with type 2 diabetes." (PMID 35216490, 2022). "On the other hand, many studies demonstrated that type 2 diabetes was associated with higher blood FGF23 levels." (PMID 35216490, 2022). "Several studies have demonstrated that in patients with type 2 diabetes, a higher circulating FGF23 level is associated with an increased risk of all-cause mortality and cardiovascular mortality." (PMID 32857288, 2020). "Subsequently, we address the known associations between FGF23 and outcomes in patients with type 2 diabetes who have either preserved or impaired kidney function." (PMID 32857288, 2020). "In patients with type 2 diabetes and normal or mildly impaired kidney function, increased levels of FGF-23 are associated with impaired cardiac diastolic function and decreased MPR, caused by a decrease in maximal MBF during stress." (PMID 32998751, 2020). "In conclusion, the present study identifies FGF23 serum levels as an independent risk factor for unstable carotid plaque in the general population with type 2 diabetes." (PMID 26459301, 2015). "Type 2 diabetes (T2D) has been associated with higher rates of cardiovascular disease, thus showing the evaluation of FGF23 and its relationship with cardiovascular disease in T2D is of interest." (PMID 26459301, 2015). "Patients with type 2 diabetes may be susceptible to abnormalities in bone and mineral metabolism including increased blood FGF23 levels." (PMID 35216490, 2022). "Among the FGF23-associated SNPs, associations were observed for the rs2769071 variant with low-density lipoprotein (P = 3.06E−10), total cholesterol (P = 7.48E−13), diastolic blood pressure (P = 2.80E−10), and type 2 diabetes (P = 2.30E−05)." (PMID 33424930, 2020). "Furthermore, a recent study of patients with type 2 diabetes and normal or mildly impaired kidney function showed that FGF-23 was associated with an increased risk of both major adverse cardiovascular events and all-cause mortality." (PMID 32998751, 2020). "Recent research highlights fibroblast growth factor 23 (FGF23) as a potential contributor to type 2 diabetes and its cardiovascular complications." (PMID 40237064, 2025). "In another study in patients with type 2 diabetes, a euglycemic-hyperinsulinemic clamp led to an increase in serum FGF23 levels." (PMID 40237064, 2025). "The study aimed to analyze and compare the concentrations of selected fibroblast growth factors, FGF-2, FGF-19, FGF-22, and FGF-23, in the plasma of patients with type 1 and type 2 diabetes with those of the control group." (PMID 40943671, 2025). "In our study, the levels of FGF-2, FGF-19, FGF-22, and FGF-23 were measured in patients with type 1 and type 2 diabetes and compared with healthy controls." (PMID 40943671, 2025). "Associations with uric acid secretion have also been reported in type 2 diabetes, and elevated FGF-23 is consistently related to poor outcomes." (PMID 40943671, 2025). "This association persists independently of other variables, as shown by strong correlations between serum FGF23 levels and atherosclerotic disease in the lower extremities of Chinese individuals with type 2 diabetes." (PMID 39221259, 2024). "Inflammation is a major trigger of FGF23 production and most type 2 diabetes patients, especially those with obesity, suffer from inflammatory conditions." (PMID 35216490, 2022). "Future studies should clarify if FGF23 is merely a disease severity marker or a contributor to adverse outcomes in type 2 diabetes and establish if antidiabetic medication can modify FGF23 levels." (PMID 32857288, 2020).
type 2 diabetes (continued). "The aim of this study was to evaluate the relationship between FGF-23 and cardiac structure, function and perfusion in patients with type 2 diabetes and normal or mildly impaired kidney function." (PMID 32998751, 2020). "Seventh, inflammation is a major trigger of FGF23 production, and most patients with type 2 diabetes, especially those with obesity, are in a pro-inflammatory state." (PMID 32857288, 2020). "This is in line with a specific role for FGF23 in patients with type 2 diabetes, even in patients with preserved or mildly impaired kidney function." (PMID 32857288, 2020). "In a previous study, we assessed FGF23 in a general population cohort, which also included type 2 diabetes patients [20••]." (PMID 32857288, 2020). "In this study, we investigated the association between FGF-23 and cardiac remodeling and subclinical cardiac disease measured by CMR in a large cohort of patients with type 2 diabetes and normal or mildly impaired kidney function." (PMID 32998751, 2020). "Our results replicate previous findings in individuals with type 2 diabetes of associations of increased levels of MMP-12, FGF-23, TNFR-1 and TNFR-2 with incident MACE." (PMID 29796748, 2018). "Thus, a potential dual role for FGF23 (deregulation) has been proposed in both the development of type 2 diabetes and its complications." (PMID 40237064, 2025). "A chronic inflammatory state may overrule the suppressive effect of hyperinsulinemia in patients with type 2 diabetes, resulting in their higher blood FGF23 levels." (PMID 35216490, 2022). "Future studies should clarify whether FGF23 is merely a disease severity marker or a contributor to adverse outcomes in type 2 diabetes and establish whether antidiabetic medication can modify blood FGF23 levels." (PMID 35216490, 2022). "However, compared with patients in the lowest FGF-23 tertile, those with higher FGF-23 levels were older, had a greater prevalence of type 2 diabetes and CKD, and were more likely to present with higher levels of serum phosphate and CRP at baseline." (PMID 34297744, 2021). "This may explain high FGF23 levels in type 1 diabetes, whereas in type 2 diabetes hyperinsulinaemia may be expected to lead to lower FGF23 levels." (PMID 32857288, 2020). "We aimed to summarize current literature on the associations between FGF23 and outcomes in patients with type 2 diabetes with or without CKD." (PMID 32857288, 2020). "However, the new method also revealed novel associations which were not apparent using the older method; levels were found to be higher in patients with type 2 diabetes and correlated strongly with serum calcium and FGF23 concentrations." (PMID 28720774, 2017). "Furthermore, in db/db mice, which are an animal model of type 2 diabetes, blocking of FGF23 action by the administration of the C-terminal tail of FGF23 improved diabetic nephropathy by decreasing inflammation and fibrosis without changing the blood levels of phosphate or FGF23." (PMID 35216490, 2022). "More recently, emerging data suggested that FGF23 levels may be specifically elevated in patients with type 2 diabetes and be associated with adverse outcomes irrespective of kidney function." (PMID 32857288, 2020). "Moreover, recent data suggest that FGF23 are elevated and may also be a risk factor for cardiovascular disease and mortality in type 2 diabetes patients without CKD, although the magnitude of the association is smaller than in CKD patients." (PMID 32857288, 2020). "Emerging data suggest that FGF23 plays a specific role in type 2 diabetes, partly independent of kidney function." (PMID 32857288, 2020). "The biomarker fibroblast growth factor-23 (FGF-23) has been associated with increased cardiovascular morbidity and mortality in both patients with and without type 2 diabetes." (PMID 32998751, 2020).
type 2 diabetes (continued). "This study aims to examine whether the predictive effect of FGF-23 is independent from circulating levels of tumor necrosis factor receptor 1 (TNFR1), a strong predictor of ESRD in Type 2 diabetes (T2D)." (PMID 23526964, 2013). "Overall, these results indicate that both age and BMI are consistently associated with reduced concentrations of FGF-19 and FGF-22, particularly in patients with type 2 diabetes, whereas FGF-2 and FGF-23 showed no consistent correlations with either parameter." (PMID 40943671, 2025).
diabetic nephropathy (29 papers, 2013 to 2026). "In our study, the association between FGF-23 and AS remained significant even after adjustments for eGFR (renal function) and the presence of microvascular complications (including diabetic nephropathy)." (PMID 26462160, 2015). "One study reported that elevated FGF-23 levels were associated with TNFR1 levels in subjects with diabetic nephropathy." (PMID 23526964, 2013). "Recent studies suggested that higher levels of FGF23 are associated with diabetic nephropathy." (PMID 28619026, 2017). "This has moved the focus from a PTH-centric view to one where the severe imbalance between FGF23 and Klotho is recognized as the dominant driver of cardiovascular and renal progression, especially in diabetic kidney disease (DKD)." (PMID 41515987, 2025). "The stimulation of IL6 and TNFα production elicited by FGF23 is abolished in diabetic nephropathy mouse models injected with the carboxy-tail peptide of FGF23, which prevents iFGF23 signaling." (PMID 38791495, 2024). "Intact serum FGF23 was a predictor of doubling of creatinine, dialysis initiation, and death in diabetic nephropathy patients." (PMID 35872753, 2022). "Another study reported that FGF23 is a significant independent predictor of the renal outcome in patients with macroalbuminuric diabetic nephropathy." (PMID 35216490, 2022). "Recent studies have provided a more detailed overview of the spectrum of bone and mineral abnormalities in diabetic nephropathy, including data on FGF23." (PMID 32857288, 2020). "In conclusion, we found that FGF23C-tail, as a competing antagonist of intact FGF23, ameliorates the development of diabetic nephropathy by improving renal dysfunction and morphologic abnormality." (PMID 29843712, 2018). "High level of serum fibroblast growth factor 23 (FGF23) is implicated in the development and progression of diabetic nephropathy (DN), making it a crucial factor in the pathogenesis of DN." (PMID 29843712, 2018). "It is of interest whether antidiabetic medication may influence FGF23 levels in diabetic nephropathy." (PMID 32857288, 2020). "Patients with diabetic nephropathy may display a specific pattern of bone and mineral disturbances, including earlier and more severe increases in FGF23 levels." (PMID 32857288, 2020). "Indeed, many studies over the past years, including studies in patients with diabetic nephropathy, have shown that FGF23 levels are increased in CKD patients, most likely in response to a reduced renal capacity to excrete phosphate." (PMID 32857288, 2020). "FGF23C-tail may improve diabetic nephropathy by decreasing inflammation and fibrosis in db/db mice, suggesting that blocking of FGF23 action remains an important therapeutic target for the prevention or attenuation of the progression of DN." (PMID 29843712, 2018). "Therefore, FGF23 may be an inflammatory marker in diabetic nephropathy, which triggers a series of pathological changes in renal tissue." (PMID 36649363, 2023). "Moreover, the elevation of FGF23 can result in inflammation in diabetic nephropathy." (PMID 36649363, 2023). "Similarly, the injection of the carboxi-tail peptide of FGF23, which prevents iFGF23 signaling, in a diabetic nephropathy mouse model reduced the renal expression as well as the serum levels of inflammatory cytokines IL6 and TNFα without affecting serum FGF23 and Pi levels." (PMID 34208131, 2021). "The present study aims to examine the expression of leukocyte adhesion molecules and FGF23, and ACE2 in the mouse kidney with Pg-LPS-induced diabetic nephropathy." (PMID 33407253, 2021). "There are several biomarkers with probable utility in the context of diabetic kidney disease (DKD), including fibroblast growth factors 21 and 23 (FGF21, FGF23) and pigment epithelium-derived factor (PEDF), which are associated with inflammatory pathways and fibrosis." (PMID 37189380, 2023).
diabetic nephropathy (continued). "Baseline level of FGF23 was found to be higher in the patients with higher glomerular filtration rate (GFR), in older patients, in males, in those patients with diabetic nephropathy, in those with acceptable renal function than in patients who suffered transplant rejection." (PMID 28497083, 2017). "Interventions aiming to optimize renin-angiogensin-aldostero system (RAAS)-blockade efficacy, such as low-sodium diet or the addition of a thiazide diuretic, may not affect FGF23 levels in diabetic nephropathy." (PMID 32857288, 2020). "In addition, focal FGF23 staining was previously observed in both proximal and distal tubular sections at a more advanced phase of the disease in a Zucker diabetic fatty (ZDF) rat diabetic nephropathy model." (PMID 29518087, 2018).
kidney damage (29 papers, 2013 to 2025). "During the early stages of CKD, the expression of the renal FGF23 co-receptor, αKlotho, decreases in response to kidney damage and progressively declines along with the loss of functional nephrons, promoting partial resistance to FGF23′s physiological actions." (PMID 31461904, 2019). "We consider that it could be due to its relationship with albuminuria since most studies associate elevated FGF-23 levels with nephropathy including albuminuria." (PMID 34065223, 2021). "Although it remains unclear whether FGF23 or its receptor may be causal factors that promote kidney damage or impair renoprotective therapy, emerging data indicate that FGF23 can have detrimental off-target effects on the heart." (PMID 32857288, 2020). "An unexpected finding was that FGF23 levels were also significantly lower in VillinCreERT2Cyp24fl/fl versus control mice with adenine-induced kidney damage." (PMID 39688907, 2024). "In our ApoE KO mice with adenine-induced nephropathy, FGF23 was increased, and Vdr and Cyp27b1 mRNA levels were down-regulated in the kidney, providing evidence for impaired bone growth conditions." (PMID 36009040, 2022). "Fibroblast growth factor 23 (FGF23) produced in bone was considered as regulator of phosphate metabolism on the kidneys, and was found to be increased with nephropathy progression in CKD population." (PMID 30278796, 2018). "Here, we use wildtype and genetically modified mice to evaluate the causal contribution of high phosphate or enhanced FGF23 levels on tubular injury, fibrosis and TLS formation and to analyze whether TLS development is directly associated with kidney damage." (PMID 41384828, 2025). "Contrariwise, mice with a single amino acid substitution-induced constitutive gain-of-function mutation in Fgfr4 develop LVH without kidney damage or increased FGF23 levels." (PMID 39807363, 2025). "This further justifies continued research on the connection between dietary sodium chloride and phosphorus metabolism in cats, especially with the knowledge that elevated FGF23 serum concentration is an early marker for kidney damage in felines and several other species." (PMID 36428422, 2022). "Because the C-terminus of FGF23 has no biological activity, it competes with intact FGF23 for binding to FGF23 receptors, which suggests that increased FGF23 levels in DN may aggravate kidney damage by promoting the activation of inflammation." (PMID 36353239, 2022). "The objective of this study was to investigate whether childhood cancer treatment affects the levels of soluble α-Klotho and fibroblast growth factor-23 in survivors of childhood cancer several years after treatment, as well as their relationship to kidney damage and cardiovascular disease." (PMID 38792509, 2024). "However, the purpose of the study was, among other things, to verify whether abnormal FGF23 secretion, which could be indicative of early kidney damage, is already observed at a young age." (PMID 38792509, 2024). "However, we think that this study makes interesting point in the discussion about FGF-23 short-term behaviour after kidney injury, showing that nephrectomy may differ from other types of kidney damage." (PMID 28130714, 2017). "Mice developed histological, serological, and functional evidence of kidney damage, decreased GFR, increased expression of kidney injury and fibrosis markers, and significantly increased levels of PTH and FGF23 compared with animals fed a control diet." (PMID 39688907, 2024). "It is known that at five weeks of age, Col4a3−/− mice do not show significant kidney damage or elevations in serum levels of phosphate and FGF23." (PMID 39273260, 2024). "We further investigated whether PMWCNT-induced kidney damage could affect bone mineral metabolism and vascular calcification, which are major categories of aging, using related serum proteins including DKK-1, FGF-23, and sclerostin." (PMID 37112600, 2023).
kidney damage (continued). "Circulating FGF23 was reported increased and klotho decreased in AKI rodent models, and treatment with klotho could improve kidney damage." (PMID 35272698, 2022). "Therefore, we investigated the relationship between markers for the Pi load in serum (serum Pi, BAP, and FGF-23) and urinary albumin excretion expressed as UACR, a clinically reliable marker for kidney damage." (PMID 29311711, 2018). "Likewise, in hypophosphatemic Hyp mice, no immune cell aggregates nor kidney damage were observed despite elevated FGF23 levels." (PMID 41384828, 2025). "Therefore, unlike in the kidney damage condition, liver is the only source of circulatory FGF23 in chronic alcohol-induced liver injury through hepatocyte specific activation of the endocannabinoid-CB1R-ERRγ signal transduction axis." (PMID 38479224, 2024). "However, in diabetic ICR mouse kidneys with Pg-LPS-induced nephropathy (LPS-STZ) the expression of VCAM-1 and the accumulation of FGF23 were observed in renal tubules and glomeruli, and the expression of E-selectin was observed in renal parenchyma and glomeruli." (PMID 33407253, 2021).